RNU6-408P (RNA, U6 small nuclear 408, pseudogene)
Gene: Small nuclear RNA gene on chromosome 18 (29,048,620 to 29,048,719, forward strand). Ensembl gene ENSG00000251719.
Homologues: Orthologues: chimpanzee U6 (100% identical), rabbit U6 (75% identical), dog U6 (74% identical), dog U6 (73% identical). Paralogues in human: RNU6-188P (81% identical), RNU6-20P (81% identical), RNU6-211P (81% identical), RNU6-836P (81% identical), RNU6-1122P (80% identical), RNU6-224P (80% identical), RNU6-812P (80% identical), RNU6-1152P (79% identical), RNU6-15P (79% identical), RNU6-203P (79% identical), RNU6-310P (79% identical), RNU6-35P (79% identical), and 1286 more.